SIRT3 (sirtuin 3)
Diseases named in the same sentence as SIRT3 in open-access papers (continued):
Sharing a sentence is not in itself a finding about the gene and the disease.
cancer (continued). "Furthermore, SIRT3's involvement in ferroptosis adds another layer of complexity to its role in cancer." (PMID 38773972, 2024). "In PDAC, where SIRT3 downregulation exacerbates metabolic dysregulation and oxidative damage, the combined approach of SIRT3 reactivation and inhibition of oncogenic signaling presents a novel, multifaceted strategy for suppressing cancer progression and improving patient outcomes." (PMID 39682281, 2024). "A previous study has demonstrated that SB inhibits SIRT3 to promote apoptosis in cancer cells." (PMID 39273544, 2024). "Conversely, in scenarios where SIRT3 supports cancer progression by enhancing oxidative phosphorylation or promoting cell survival mechanisms, SIRT3 inhibitors might be more appropriate." (PMID 38773972, 2024). "There are many challenges in targeting SIRT3 for cancer treatment, such as whether these compounds can enter clinical trials, and further in vitro and in vivo evaluations of their antitumor activity and toxicities are needed." (PMID 38773972, 2024). "However, the application of compound 8 for cancer therapy requires a further investigation of the effect and specific mechanism of compound 8 on cancer after inhibiting SIRT3." (PMID 38773972, 2024). "SIRT3 KO mice were reported to have significantly shorter lifespans than wild-type mice and spontaneously show an accelerated development of age-related disorders including metabolic syndrome, cardiovascular disease, cancer, and neurodegenerative diseases." (PMID 39683482, 2024). "SIRT3 plays a role in multiple fundamentalfeatures of cancer." (PMID 38261767, 2024). "Moreover, SIRT3 inhibitors also play an important role for treating cancer, and the SIRT3 inhibitor development methodologies are more varied compared to SIRT3 activators." (PMID 38773972, 2024). "However, if cancer cells produce ROS through other pathways or in response to external stresses, then SIRT3 accumulation can be exploited by cancer cells to maintain ROS at a non-toxic level." (PMID 38931477, 2024). "SIRT3 is involved in most of these cancer pathways, making it a promising new therapeutic target." (PMID 38816444, 2024). "A plethora of work that has been done around sirtuins revolves around cancer research, and it has been found that SIRT3 knockout cells have, in fact, higher levels superoxide radicals and are prone to being genetically vulnerable and more likely to develop tumors." (PMID 36952068, 2024). "Interestingly, SIRT3 has been shown to promote or inhibit cancer development based on the type of cancer and the different signaling pathways." (PMID 38931477, 2024). "Indeed, recent cancer studies have tried to improve cancer treatment results through SIRT3-enhanced expression." (PMID 37345199, 2023). "In summary, our study not only provides a potential strategy for cancer therapy by targeting the K70 site of ALDH1L2 but also suggests that the combination of SIRT3 inhibitor and 5-Fu may overcome 5-Fu resistance." (PMID 37507016, 2023). "SIRT3 participates in reprogramming of cancer cell metabolism by activating the ROS/HIF-1α pathway: SIRT3-mediated decrease in ROS level induces activation of oxygen-dependent prolyl hydroxylases (PHD) with subsequent degradation of hypoxia-induced factor 1-α (HIF-1α)." (PMID 37175631, 2023). "Similarly, mechanisms of maintaining activity through PTM regulation, as demonstrated by SIRT3, also support the metabolic needs of cancer cells and should be considered for targeting cancer-specific metabolic dependencies." (PMID 37949226, 2023). "Remarkable findings report that SIRT3 regulate cancer metabolism rewiring by modulating the acetylation of several enzymes sustaining glycolysis and through the activation of the AMPK/PPAR pathway that, triggering FA synthesis, ultimately promotes cancer metastasis." (PMID 37735413, 2023). "However, at the same time, numerous studies have shown that the SIRT3 expression also correlates with a good outcome in the treatment of many types of cancer." (PMID 37175631, 2023).
cancer (continued). "Moreover, SIRT3 overexpression inhibits the growth and induces apoptosis of cancer cells, increases their sensitivity to chemotherapeutic agents." (PMID 37175631, 2023). "Finally, we found a significant upregulation of MST1 and downregulation of SIRT3 levels in human myocardial tissue of cancer patients treated with DOX." (PMID 37566283, 2023). "This highlights the importance of SIRT3 in the development of these types of cancers." (PMID 37175631, 2023). "In addition, SIRT3 also plays a proapoptotic role in a range of human cancer cell lines derived from colorectal cancers and osteosarcoma." (PMID 37196115, 2023). "The roles of SIRT3 vary in different types of cancers and they have been thoroughly discussed." (PMID 37608150, 2023). "SIRT3 could reprogram cancer cell metabolism through HIF1α destabilization or suppress HIF‐1α by reducing mitochondrial ROS." (PMID 36383055, 2023). "In different cancer pathological types, SIRT3 may trigger different key proteins and signaling pathways to initiate oncogenic or antitumor effects." (PMID 37747648, 2023). "By studying the mechanistic differences in various cancer types, our understanding of the carcinogenic and anticancer effects of SIRT3 may deepen, which can aid the development of novel cancer therapeutic strategies." (PMID 35571098, 2022). "Overall, the dual role of SIRT3 may render the utility of SIRT3 as a target of cancer treatment uncertain." (PMID 35571098, 2022). "Furthermore, we offer an effective evidence-based basis for the evolvement of potential personalized therapy management strategies for SIRT3 in cancer settings." (PMID 35832551, 2022). "However, to the best of our knowledge, no study investigated the correlation between the expressions of KAT6A and SIRT3 in cancer, despite their potential importance in tumorigenesis." (PMID 35422864, 2022). "In contrast, SIRT3 plays the role of an oncogene in some cancers." (PMID 35178152, 2022). "Our results underline that SIRT3 effects can be highly cancer cell context specific, a point that is nicely illustrated by the lack of effect of SIRT3 depletion on HIF1α functions in DLBCL cells." (PMID 35019856, 2022). "In this review, we mainly pay close attention to how SIRT3 plays a dual role in regulating the cancer metabolism reprogramming, metastasis, and chemoresistance, as well as further summarize the SIRT3 small molecule modulators in the application of cancer therapy." (PMID 35832551, 2022). "In addition, the personalized therapy combined application of SIRT3 small molecule modulators with the other drug targeting a specific cancer type has a promising future for the patients." (PMID 35832551, 2022). "Thus, the Sirt3/FOXO3a/SOD2 axis of the mitochondrial unfolded protein response (UPRmt) was activated in cancer cells in response to oxidative proteotoxic stress in mitochondria, increasing mitochondrial fitness and supporting metastasis." (PMID 35938164, 2022). "Therefore, altered miRNA expression affects the signaling pathway of SIRT3 involved in cancer progression." (PMID 35832551, 2022). "Recently, owing to its dual role in cancer, SIRT3 has attracted extensive attention." (PMID 35832551, 2022). "In fact, SIRT3 is heavily involved in various physiological metabolic processes through deacetylation, and thus involved in the process of several diseases of aging, including cancer, heart diseases, metabolic diseases, etc.." (PMID 36010672, 2022). "Given that HIF1α has oncogenic roles in multiple cancer types, we wondered whether HIF1α might be modulated by SIRT3 in DLBCLs as well." (PMID 35019856, 2022).
cancer (continued). "In recent years, butyrate has been recognized as a SIRT3 inhibitor promoting cancer cell apoptosis and treatment with butyrate inhibited the ability of SIRT3 to deacetylate a synthetic acetylated pyruvate dehydrogenase E1α subunit (PDHA1) peptide containing K336." (PMID 35571098, 2022). "SIRT3 plays a significant inhibitory role in the cancer metastasis process." (PMID 35832551, 2022). "The Si-RNA interference of SIRT3 in cancer cells was performed." (PMID 35865961, 2022). "In this review, we emphasize the role of SIRT3 in tumorigenesis and cancer therapy." (PMID 35571098, 2022). "Understanding the critical role of SIRT3 in different cancer types may help to enhance our knowledge of carcinogenic and anticancer effects." (PMID 35571098, 2022). "SIRT3 is downregulated and contributes in both cancer development and progression in ccRCC." (PMID 35671305, 2022). "Furthermore, we provide evidence to support the development of potential personalized therapy strategies for SIRT3 in cancer settings." (PMID 35832551, 2022). "However, the function of SIRT3 varies in different cancer types or at different stages of the same cancer type, which makes it relatively difficult for cancer therapy to target SIRT3." (PMID 35832551, 2022). "SIRT3 plays a dual role in cancer, and whether it promotes or suppresses tumors probably depends on the type of cancer and the status of intracellular signaling pathways." (PMID 35571098, 2022). "SIRT3 is capable of metabolic reprogramming and contributes greatly in the fate of cancers." (PMID 35927590, 2022). "It is not fully understood whether the SIRT-3 relative anti-oxidative pathway may play a role in the anti-cancer effect of RES and cis-DDP combination." (PMID 35865961, 2022). "Exploring the function of SIRT3 in the field of cancer continues to enrich our knowledge bases." (PMID 35832551, 2022). "Both Cambinol and NƐ-acyl-lysine analogs are all SIRT3 inhibitors with promising anti-cancer potential, but their anti-cancer mechanism remains unclear." (PMID 35832551, 2022). "Cancer cells usually possess higher ROS levels than normal cells, and the upregulation of SIRT3 in tumors may be to reduce oxidative damage and enhance the mitochondrial stress defense system in some cases." (PMID 35571098, 2022). "Therefore, the development and application of targeted SIRT3 as a small molecule of anti-cancer drugs has been a hotspot for many researchers." (PMID 35832551, 2022). "There are few reports about SIRT3 activators in cancer treatment." (PMID 35832551, 2022). "Thus, melatonin induces cancer cellular apoptosis by elevating ROS generation due to an increase in OXPHOS through the stimulation of SIRT3 activity." (PMID 36009340, 2022). "Here, many other types of SIRT3 inhibitors have also been reported for cancer treatment." (PMID 35832551, 2022). "Sirt3 can function as an oncogene and support cancer cell proliferation." (PMID 35938164, 2022). "SIRT3 improves the sensitivity of cancer cells to chemotherapy to inhibit drug resistance." (PMID 35832551, 2022). "SIRT3 is a potential target for new therapies for treating cancer." (PMID 35571098, 2022). "Finally, in addition to regulating metabolism reprogramming and EMT, there are other potential mechanisms that SIRT3 participates in cancer metastasis." (PMID 35832551, 2022). "It remains to be investigated whether Sirt3 regulates cancer cell migration and metastasis through controlling succinate accumulation and/or secretion." (PMID 36344992, 2022). "Nrf2 and Sirtuin 3 (Sirt3) expressions are correlated with redox imbalance in cancer cells." (PMID 34770867, 2021). "Conversely, higher expression of SIRT3 has been reported in cancers of esophagus, breast and colon." (PMID 33937086, 2021). "SIRT3 may also have oncogenic activity by regulating ROS levels to prevent apoptosis, thereby enhancing the survivability of cancer cells." (PMID 34831420, 2021).
cancer (continued). "Recently, Sirt3 was found to be involved in cancer development and progression 8,21." (PMID 34405009, 2021). "SIRT3 promotes cancer cell survival by inhibiting apoptosis." (PMID 34795840, 2021). "SIRT3 promotes cancer cell apoptosis through destabilizing HIF1α." (PMID 34795840, 2021). "Interestingly, the upstream analysis of SIRT3-modulated genes identified in our PCR array predicted the inhibition of HIF1α, further supporting the involvement of SIRT3-HIF1α-ROS connection in cancer metabolism." (PMID 33937086, 2021). "In HNSCC and DLBCL cells, SIRT3 inhibitors have potently hindered cancer growth." (PMID 34650436, 2021). "As such, the role of SIRT3 is likely context and cancer type dependent." (PMID 34650436, 2021). "Since SIRT3 can maintain the production of ROS at an appropriate level to prevent cell apoptosis and promote cell proliferation, it is called an oncogene in certain types of cancer." (PMID 34841698, 2021). "SIRT3 and SIRT7 expression was correlated with high proliferation rates in the GCT samples, and these two SIRT family members have also been implicated in different cancers." (PMID 33669567, 2021). "Recently, accumulating studies have revealed that SIRT3 prevents the formation of cancer cells." (PMID 33819917, 2021). "Several reports suggest that SIRT3 has a dual role in cancer." (PMID 32306906, 2020). "Conversely, SIRT3 has been shown to increase lactate and ATP production, leading to increased glycolysis, which together with increased mitochondrial MnSOD and decreased intracellular ROS promote the proliferation of cancer cells." (PMID 33178616, 2020). "So far, the effect of SIRT3 on glucose metabolism has been studied in cancers other than HCC." (PMID 32306906, 2020). "SIRT3 was deleted or down-regulated in many types of human cancers." (PMID 32158696, 2020). "In addition, because a few compounds have been explored to modulate SIRT3 activity, we also attempted to identify effective compounds that increase the endogenous SIRT3 modulation mediated by the anti-cancer effect of sorafenib." (PMID 32306906, 2020). "In this regard, regulation of SIRT3 expression might be a novel strategy to investigate more personalized therapies against cancers." (PMID 32306906, 2020). "SIRT3 is also involved in the overall progression of cancer." (PMID 32724473, 2020). "Accordingly, in most glycolysis-addiction cancers, SIRT3 activation will be beneficial and SIRT3 activators might be candidate adjuvants." (PMID 32724473, 2020). "As noted, the effect of A671 on SAP18 and SIRT3 was cancer-specific." (PMID 33273692, 2020). "Accordingly, we should be thoughtful in trying to regulate SIRT3 for cancer therapy." (PMID 32724473, 2020). "The impact of these compounds on SAP18 stability and the SAP18/SIRT3 ratio may serve as indicators for survival and drug response in other cancer types." (PMID 33273692, 2020). "We next aimed to investigate whether upregulation of SIRT3 by the CDK4/6 inhibitor PD0332991 could enhance the anti-cancer effect of sorafenib on HCC cells." (PMID 32306906, 2020). "It has been shown in recent studies that in some highly malignant tumors, the activation of SIRT3 might be a possible treatment method, especially for some drug-resistant cancers." (PMID 32724473, 2020). "Given the different functions regulated by SIRT2 and SIRT3, unraveling downstream targets/pathways involved may provide opportunities to develop new strategies for cancer prevention." (PMID 31970087, 2019).
cancer (continued). "SIRT3 controls the acetylation status of different proteins regulating mitochondrial metabolism, oxidative stress, and ROS production, thereby preventing apoptosis, growth arrest, and senescence, and promoting cancer cell proliferation." (PMID 30761005, 2019). "In glucose deprivation conditions, metformin sensitized cancer cells by inhibiting mitochondrial complex I, reducing the accumulation of unfolded proteins in the endoplasmic reticulum and promoting the activation of SIRT3." (PMID 30909600, 2019). "In different types of cancers including colon, gastric, renal, oral squamous, and esophageal cancer and melanoma, SIRT3 expression is upregulated, determining an alteration of many important biological processes and correlating with high tumor grade, positive lymph node status, and poor prognosis." (PMID 30761005, 2019). "Several studies describe a crucial role for SIRT3 in cancer development and progression." (PMID 30761005, 2019). "SIRT3−/− MEF study demonstrates that cancer cells consume more glucose." (PMID 30538800, 2018). "SIRT3 destabilizes HIF1α induced metabolic reprogramming in cancer cells." (PMID 30250024, 2018). "SIRT3 can exert controls on a wide range of important biological activities including regulation of nuclear gene expression, metabolic control, neuroprotection, cardiovascular disease, cancer, and aging." (PMID 27686535, 2017). "Here, we report that butyrate promotes cancer cell apoptosis by acting as a SIRT3 inhibitor." (PMID 29263907, 2017). "This study aims to provide a comprehensive review of the most relevant biological and pathophysiological functions of SIRT3 such as cancer control, neuroprotection, DNA repair, enhanced longevity, energy homoeostasis, oxidative stress tolerance, and many other mechanisms." (PMID 27686535, 2017). "In this way, some studies report that SIRT3 silencing results in a decreased cellular proliferation and induces cell death, hence it could improve chemotherapy efficacy for some cancers." (PMID 28704962, 2017). "Besides its function in metabolism regulation, SIRT3 has been referred to as an oncogene in some types of cancer, as SIRT3 can maintain ROS production at the appropriate levels to prevent apoptosis and promote cell proliferation." (PMID 28704962, 2017). "SIRT3 which controls the activation and deactivation of many important enzymes is related to the levels of reactive oxygen species (ROS) in the mitochondria and offers significant protection against aging and cancer." (PMID 28947845, 2017). "Furthermore, some studies in tumors report a correlation between SIRT3 expression and the evolution of several types of cancer." (PMID 28704962, 2017). "Furthermore, SIRT3 knockdown sensitizes cancer cells to cytotoxic treatments and reduces cell proliferation." (PMID 28704962, 2017). "On the other hand, SIRT3 possesses the potential to regulate the cancer processes and may be the therapeutic target for cancer." (PMID 28600541, 2017). "In this regard, modulation of SIRT3 activity could be a new target to develop more personalized therapies against cancer." (PMID 28704962, 2017). "These patient data strongly support our hypothesis that activation of the SIRT3 axis of the UPRmt increases the invasiveness and metastatic potential of cancer cells." (PMID 28798902, 2017). "For example, it has been demonstrated that increased SIRT3 expression is found in cancer such as oral squamous cell carcinoma and melanoma, suggesting that this could lead to concomitant increases in SOD2 activity." (PMID 29099803, 2017). "Contrary to these observations, activation of SIRT3 can also confer protection to cancer cells." (PMID 28423723, 2017). "Apart from its role in cardiac protection, SIRT3's role in cancer metabolism is also well studied." (PMID 28423723, 2017). "To date, the most remarkable feature of SIRT3 is its ability to suppress tumors and/or cancer." (PMID 27686535, 2017).